DDX49 (DEAD-box helicase 49)
Description:
ATP-dependent RNA helicase that plays a role in various aspects of RNA metabolism including the regulation of mRNA export and the levels of pre-ribosomal RNA. Regulates the stability and synthesis of pre-ribosomal RNA and thereby regulates cell proliferation. Also possesses antiviral activity by recognizing gammaherpesvirus transcripts in the context of lytic reactivation.
Synonyms: FLJ10432; Dbp8; R27090_2
Tractability: PROTAC: ubiquitination databases record sites on it; its protein half-life has been measured.
Gene: Protein-coding gene on chromosome 19 (18,919,700 to 18,929,189, forward strand). Ensembl gene ENSG00000105671.
Subcellular location: Nucleus, nucleolus
Subcellular location (Human Protein Atlas): Mitochondria
Pathways (Reactome):
Metabolism of RNA: Major pathway of rRNA processing in the nucleolus and cytosol; rRNA modification in the nucleus and cytosol
Gene Ontology:
Molecular function: ATP hydrolysis activity; protein binding; RNA binding; RNA helicase activity; ATP binding; nucleic acid binding
Biological process: positive regulation of cell growth; regulation of rRNA stability
Cellular component: nucleoplasm; nucleolus
Genetic constraint (gnomAD): Loss-of-function variants: 50 observed, 53 expected, observed/expected ratio (o/e) 0.94, 90% interval 0.75 to 1.19. The upper end of that interval is the gene's LOEUF score, 1.19, which puts it in group 5 of 6, group 1 being the genes least tolerant of losing a copy. Missense variants: 614 observed, 629.78 expected, observed/expected ratio (o/e) 0.97, 90% interval 0.91 to 1.04. Synonymous variants: 269 observed, 262.94 expected, observed/expected ratio (o/e) 1.02, 90% interval 0.93 to 1.13.
Homologues: Orthologues: chimpanzee DDX49 (100% identical), pig DDX49 (96% identical), dog DDX49 (94% identical), macaque DDX49 (93% identical), guinea pig DDX49 (91% identical), mouse Ddx49 (90% identical), rat Ddx49 (89% identical), tropical clawed frog ddx49 (80% identical), zebrafish ddx49 (73% identical), Caenorhabditis elegans H20J04.4 (48% identical), Drosophila melanogaster Dbp45A (47% identical). Paralogues in human: DDX47 (41% identical), DDX54 (33% identical), DDX17 (30% identical), DDX27 (30% identical), DDX31 (29% identical), DDX5 (29% identical), DDX42 (29% identical), DDX24 (28% identical), DDX46 (28% identical), DDX56 (28% identical), DDX3X (28% identical), DDX4 (27% identical), and 26 more.
Diseases named in the same sentence as DDX49 in open-access papers:
DDX49 is named in the same sentence as 20 diseases in open-access papers, as found by Europe PMC text mining. Sharing a sentence is not in itself a finding about the gene and the disease. The quoted sentences say what the papers report.
breast carcinoma (4 papers, 2018 to 2025). "DDX49 is one such uncharacterized RNA helicase, which has been implicated in viral infections and breast cancers in high throughput screens, suggesting an important physiological role." (PMID 29618122, 2018). "Further, DDX49 seems to promote the stemness of breast cancer stem cells by regulating the expression of proteins such as Oct3/4 and Sox-2 and promoting disease progression." (PMID 29618122, 2018). "DDX49 expression among breast cancer patients was also markedly increased." (PMID 37106339, 2023). "Elevated expression of DDX49 is observed in breast cancer patients." (PMID 29618122, 2018). "In addition, DDX49 may promote the growth of breast cancer stem cells by regulating the expression of Oct3/4, SOX-2 and other proteins, thus promoting the development of the disease." (PMID 37106339, 2023). "Specifically, DDX49 mRNA was upregulated in more than 10 cancer types, such as bladder cancer (BLCA), breast cancer (BRCA), and cervical squamous cell carcinoma (CESC)." (PMID 41438987, 2025).
lung adenocarcinoma (4 papers, 2020 to 2023). A carcinoma that arises from the lung and is characterized by the presence of malignant glandular epithelial cells. "We found that DDX49 was upregulated in lung adenocarcinoma tissues compared with paracancerous tissues (P < 0.05)." (PMID 33089952, 2020). "Our findings demonstrate that SNHG20/miR‐342/DDX49 axis plays an important role in lung adenocarcinoma, providing a novel insight into the treatment of lung adenocarcinoma." (PMID 33089952, 2020). "SNHG20 regulates DDX49 expression via sponging miR‐342 to regulate cell proliferation, migration and apoptosis in lung adenocarcinoma." (PMID 33089952, 2020). "In conclusion, SNHG20 was found to play an oncogenic role in the regulation of lung adenocarcinoma cell proliferation, invasion and apoptosis through targeting miR‐342/DDX49 axis." (PMID 33089952, 2020). "SNHG20 regulated lung adenocarcinoma cell proliferation, invasion and promoted cell apoptosis via miR‐342/DDX49 axis." (PMID 33089952, 2020). "In order to explore the interaction between SNHG20, miR‐342 and DDX49 in lung adenocarcinoma, the expression of DDX49 was calculated when cotransfected with shRNA‐SNHG20 and pcDNA3.1‐DDX49 in A549 cells." (PMID 33089952, 2020). "In this study, we discovered that DDX49 was overexpressed in lung adenocarcinoma tissues and cell lines in comparison with paracancerous tissues and normal cells." (PMID 33089952, 2020). "SNHG20 and DDX49 were overexpressed, while miR‐342 was lowly expressed in lung adenocarcinoma tissues and cell lines." (PMID 33089952, 2020). "Knockdown of SNHG20 by sponging miR-342 and upregulating DDX49 could promote cell apoptosis in lung adenocarcinoma." (PMID 34367998, 2021). "Knockdown of DDX49 inhibited the progression of lung adenocarcinoma." (PMID 33089952, 2020). "In addition, DDX49 participated in forming the SNHG20/miR-342/DDX49 axis, thereby participating in the positive regulation of lung adenocarcinoma cell proliferation, invasion and apoptosis." (PMID 35096017, 2021). "MiR‐342 directly targeted DDX49 and the expression of miR‐342 had negative connection with DDX49 in lung adenocarcinoma tissues." (PMID 33089952, 2020). "DDX49 was found to have negative connection with miR‐342 expression (P < 0.05), and was positively related to SNHG20 expression in lung adenocarcinoma (P < 0.05)." (PMID 33089952, 2020).
lung carcinoma (3 papers, 2020 to 2023). "We found DDX49 was associated with the lymph node metastases in lung cancer by the Akt/β‐catenin pathway." (PMID 31749282, 2020). "Three genes (BDH1, DDX49 and EGFR) were associated with lymph node metastases of lung cancer, and BDH1 gene had a highest predictive capacity for lymph node metastases and distant metastases through multivariate logistic regression." (PMID 36919822, 2023). "In the present study, we integrated transcriptome sequencing data of lymph node metastases in lung cancer and an independent sample from TCGA data to identify DDX49 gene and validated the biological function." (PMID 31749282, 2020). "In conclusion, DDX49 was a novel predictor for diagnosing lymph node metastases of lung cancer; thus, the marker can be used to improve or even replace enhanced CT for the diagnosis of lymph node metastases." (PMID 31749282, 2020). "Then, we investigated the role of DDX49 in cell proliferation, migration and invasion in lung cancer cells by a lentivirus‐knockdown assay." (PMID 31749282, 2020). "The mechanism research found downexpression of DDX49 decreased the Akt/β‐catenin pathway in lung cancer cell." (PMID 31749282, 2020). "The identification of DDX49 gene that can predict lymph node metastases in patients with lung cancer may reveal a new target of therapy for lung cancer with lymph node or distant metastases." (PMID 31749282, 2020). "Taken together, these findings suggested that DDX49 may be useful as a novel biomarker of lymph node metastases and a therapeutic target in lung cancer." (PMID 31749282, 2020). "The DDX49 gene was correlated significantly with lymph node metastases of lung cancer." (PMID 31749282, 2020). "In our research, we found that DDX49 may be useful as a novel biomarker of lymph node metastases and therapeutic target for lung cancer metastasis." (PMID 31749282, 2020). "Taken together, DDX49 was differentially expressed in positive versus negative lymph node metastases, expressed in lung cancer cell, and associated with the proliferation and lymph node metastases of lung cancer in the exon sequencing data of 188 patients from TCGA." (PMID 31749282, 2020).
lymph node metastases (3 papers, 2020 to 2025). "In this study, we observed that DDX49 was highly expressed in CRC tissues, with its expression level significantly correlating with adverse clinicopathological features (including tumor stage and lymph node metastasis) and worse patient survival." (PMID 41438987, 2025).
cervical cancer (2 papers, 2018 to 2025). A primary or metastatic malignant neoplasm involving the cervix. "To test if the nucleolar localization of DDX49 was cell-type specific, we expressed GFP tagged DDX39B and DDX49 in other cell lines such as cervical cancer derived HeLa and glioblastoma derived U251MG." (PMID 29618122, 2018). "Recent studies have revealed that DDX49 is also highly expressed in hepatocellular carcinoma and cervical cancer, where it promotes cell proliferation, implying that it may act as a pan-cancer oncogene." (PMID 41438987, 2025).
viral infection (2 papers, 2020 to 2022). "It is well established that RIG-I interacts with RNAs during viral infection, and therefore we asked whether DDX24 and DDX49 also directly interact with viral RNAs." (PMID 36298642, 2022). "To address whether recognition of KSHV transcripts by DDX24 and DDX49 plays a role in the innate immune response, we tested whether type I interferon is induced in response to KSHV IE and E mRNAs, identified by our RIPseq data, in the absence of viral infection." (PMID 36298642, 2022).
colorectal cancer (1 paper, 2025). A primary or metastatic malignant neoplasm that affects the colon or rectum. "However, despite these findings, the role of DDX49 in colorectal cancer remains largely unexplored, with no comprehensive studies conducted to date." (PMID 41438987, 2025).
liver cancer (1 paper, 2021). An epithelial or non-epithelial malignant neoplasm that arises from the liver. "Comparison of paired tumor samples and normal liver tissue from patients with HCC in Barcelona Clinic Liver Cancer (BCLC) stage A showed that DDX49 levels were significantly higher in cancerous tissues." (PMID 33952717, 2021).
prostate carcinoma (1 paper, 2023). A carcinoma that arises from epithelial cells of the prostate gland. "Nevertheless, the function of DDX49 in prostate cancer (PCa) is unknown." (PMID 37106339, 2023).
proteinopathies (1 paper, 2018). "The interaction of DDX49 with proteins known to be involved in neurological disorders such as Huntingtin-associated protein 1 (HAP1) and Amyloid-beta protein APP suggests that DDX49 might also have a role in diverse proteinopathies." (PMID 29618122, 2018).
cancer (5 papers, 2018 to 2025). A tumor composed of atypical neoplastic, often pleomorphic cells that invade other tissues. "Analogously, another group reported that up-regulation of DDX49 may be linked to increase cell proliferation in HeLa DDX49 overexpression cancer cells." (PMID 33952717, 2021). "Pan-cancer data were obtained from The Cancer Genome Atlas (TCGA) database to compare expression differences of DDX49 across 33 types of cancers." (PMID 41438987, 2025). "Previous studies have firmly established the significant overexpression of DDX49 across diverse cancer types, strongly indicating its potential involvement in cellular oncogenic transformation." (PMID 41438987, 2025). "During the comparative analysis of pan-cancer results, DDX49 was identified to exhibit high expression in CRC." (PMID 41438987, 2025). "Human DDX49 is emerging as a novel marker and therapeutic target in cancers, and as a target for anti-retroviral treatment, because it supports replication of human immunodeficiency viruses within human cells." (PMID 39698160, 2024). "Using CRISPR-Cas9 genetic editing, we show that a heterozygous (DDX49+/−) U2OS cell line is defective at cell migration, a phenotype supporting the association of DDX49 with cancer cell invasiveness." (PMID 39698160, 2024). "Human DDX49 is an emerging target in cancer progression and retroviral diseases through its essential roles in nucleolar RNA processing." (PMID 39698160, 2024). "We were unable to generate fully deleted DDX49 human U2OS cells using CRISPR-Cas9, consistent with the essentiality of DDX49 in Human Cancer Dependency Mapping, and demonstrated for Dbp8p in S. cerevisiae." (PMID 39698160, 2024). "Strikingly, DDX49 is significantly elevated in diverse cancer types suggesting that the increased abundance of DDX49 has a role in oncogenic transformation of cells." (PMID 29618122, 2018). "Analysis of pan-cancer genomic datasets, including TCGA and GTEx, revealed that the DDX49 gene was aberrantly overexpressed across multiple human malignancies, with transcriptional levels significantly dysregulated in tumor tissues compared to their normal counterparts (P < 0.05)." (PMID 41438987, 2025). "This property of DDX49 may be hijacked in cancer to promote uncontrolled cell proliferation, consistent with numerous studies." (PMID 37106339, 2023). "In this study, we also showed a decreased level of SAPK/JNK phosphorylation, indicating that SAPK/JNK may participate in the cancer-promoting function of DDX49 in PCa." (PMID 37106339, 2023). "Our results not only identify DDX49 as contributing to the disease, but they describe an anti-cancer pathway through which morphine works, which may guide further research and therapies for HCC." (PMID 33952717, 2021). "In this regard, our findings that DDX49 is upregulated in diverse cancers as well as over-expression of DDX49 promotes proliferation, suggests that DDX49 could have an oncogenic role." (PMID 29618122, 2018). "This prompted us to speculate that an increase in the levels of DDX49 could contribute to cancer manifestation." (PMID 29618122, 2018). "Indeed, we find a significant upregulation of DDX49 in diverse cancer types when we investigated pan cancer differential gene-expression data." (PMID 29618122, 2018). "Taken together, this study shows the physiological role of DDX49 in regulating distinct steps of mRNA and pre-ribosomal RNA metabolism and hence translation and potential pathological role of its dysregulation, especially in cancers." (PMID 29618122, 2018). "Since DDX49 regulates the translational efficiency, this attribute could be potentially hijacked in cancers for promoting uncontrolled cell proliferation." (PMID 29618122, 2018). "This prompted us to investigate whether DDX49 has a regulation role in cancer metastasis." (PMID 33952717, 2021).
cancer (continued). "Therefore, DDX49 might serve not only as an attractive oncotarget for cancer therapy but also as a potential biomarker for diagnosis and prognosis of various cancers." (PMID 29618122, 2018). "Our results suggest that DDX49 contributes to HCC, and that morphine may exert anti-cancer effects by down-regulating it." (PMID 33952717, 2021).
tumor (5 papers, 2020 to 2025). "The association between DDX49 and the mitochondria-associated protein TIMM44 suggests that DDX49 may indirectly regulate tumor signaling pathways by modulating mitochondrial functions, including energy metabolism and oxidative stress." (PMID 41438987, 2025). "IHC staining results demonstrated that DDX49 expression was significantly higher in CRC tumor tissues than in adjacent normal tissues (P < 0.05)." (PMID 41438987, 2025). "The expression levels of DDX49 between PCa tumour tissues and normal tissues were compared based on the TCGA-PRAD cohort, which contained the transcription profiles of 497 tumour tissues and 52 normal tissues." (PMID 37106339, 2023). "We further show that DEAD-box helicase 49 (DDX49) is up-regulated in HCC tumors, and that knocking down the DDX49 gene decreases tumor formation in vivo and in vitro, as well as reduces tumor metastasis in vivo." (PMID 33952717, 2021). "Analysis of tumor size after 6 weeks showed that knocking down DDX49 led to significantly smaller tumors (P < 0.05)." (PMID 33952717, 2021). "Here we provide evidence that morphine does inhibit HCC tumor proliferation and metastasis, and that it exerts these effects in part by down-regulating DEAD-box helicase 49 (DDX49), which we describe here for the first time as up-regulated in HCC." (PMID 33952717, 2021). "This study focuses on DDX49, an RNA helicase belonging to the DEAD-box family, and systematically explores its expression patterns, clinical prognostic value, and regulatory mechanisms underlying tumor cell proliferation in CRC." (PMID 41438987, 2025). "Accordingly, to explore whether DDX49 functions as an oncogene, we investigated the role of DDX49 in tumor cell proliferation using cytological and molecular biology techniques." (PMID 41438987, 2025). "DDX49 was significantly increased in PCa tumour tissues (p < 0.001)." (PMID 37106339, 2023). "We observed that down‐regulation of DDX49 significantly decreased tumour growth in vivo." (PMID 31749282, 2020). "However, whether DDX49 influences tumor cell proliferation through TIMM44 remains to be elucidated." (PMID 41438987, 2025). "Knocking down DDX49 inhibited HCC tumor growth and metastasis, while overexpressing it reinforces tumor growth and metastasis." (PMID 33952717, 2021). "The results showed that DDX49 expression was significantly upregulated in CRC tumor tissues compared with adjacent non-cancerous tissues." (PMID 41438987, 2025). "In other tumor types not explicitly listed, DDX49 demonstrated consistently elevated expression in neoplastic tissues versus adjacent non-tumor tissues." (PMID 41438987, 2025). "The results showed that DDX49 expression in CRC tissues was not significantly correlated with parameters such as tumor size, histological grade, and vascular invasion (all P > 0.05)." (PMID 41438987, 2025). "DDX49, a potential prognostic biomarker, promotes cell proliferation by TIMM44-PI3K-AKT pathway, which may offer a target for clinical anti-tumor therapy." (PMID 41438987, 2025). "Another study showed morphine could down-regulate DEAD-box helicase 49 (DDX49) expression and mitogen-activated protein kinases (MAPK) signaling to exert anti-tumor effect." (PMID 36713494, 2022).
infection (2 papers, 2022 to 2024). The state of being infected such as from the introduction of a foreign agent such as serum, vaccine, antigenic substance or organism. "The DDX24 and DDX49 helicases were observed to bind to several identical KSHV RNAs during lytic infection with varying degrees." (PMID 36298642, 2022). "DDX24 and DDX49 also interact with viral RNA to control infections." (PMID 39212449, 2024). "However, during infection with Kaposi’s sarcoma-associated herpesvirus (KSHV), DDX24 and DDX49 bind to multiple KSHV mRNAs and reduce viral reactivation." (PMID 39212449, 2024). "Understanding the molecular mechanisms by which DDX24 and DDX49 inhibit reactivation could lead to therapeutic strategies for EBV and KSHV malignancies whose pathogenesis is driven by both the latent and lytic phases of infection." (PMID 36298642, 2022).
DDX49 also shares sentences with these, for which no sentence is quoted: hepatocellular carcinoma (2 papers); bladder cancer (1); cervical squamous cell carcinoma (1); glioblastoma (1); Kaposi's sarcoma (1); migraine (1); neurological disorders (1).